TGFB1 (transforming growth factor beta 1)
Diseases named in the same sentence as TGFB1 in open-access papers (continued):
Sharing a sentence is not in itself a finding about the gene and the disease.
joint diseases (8 papers, 2010 to 2026). "Taken together, our results suggest that the effects of GZZSZTW on treating joint diseases might be achieved through the TGFB1/RHO interaction network coupled with other proteins and signaling pathways that were identified in this study." (PMID 31485261, 2019). "Our results suggest that the effects of GZZSZTW on treating joint diseases might be achieved through the TGFB1/RHO interaction network coupled with other proteins and signaling pathways responsible for cartilage development, growth and repair." (PMID 31485261, 2019). "Our findings indicated that the effects of GZZSZTW on treating joint diseases might achieved though the TGFB1/RHO interaction network coupled with other proteins and signaling pathways responsible for chondrogenesis, chondrocyte proliferation and differentiation and cartilage repair." (PMID 31485261, 2019). "Therefore, our results suggest that the therapeutic effects of GZZSZTW on joint diseases might be achieved through the TGFB1/RHO interaction network, which coordinately interact with multiple proteins and signaling pathways responsible for cartilage development, growth and repair." (PMID 31485261, 2019).
retinal detachment (8 papers, 2013 to 2025). An eye emergency condition which may lead to blindness if left untreated. "This may suggest that TGFβ1 dysregulation may be a ‘final common pathway’ in the pathogenesis of retinal detachment in patients with a genetic predisposition." (PMID 30568244, 2019). "The interaction between BMP4 and TGFβ1 may be important in its role in pathogenesis of retinal detachment." (PMID 30568244, 2019).
SARS-CoV infection (8 papers, 2008 to 2023). "The ROS-mediated activation of transforming growth factor beta 1 (TGF-β1) promoter during SARS-CoV infection has been documented." (PMID 34204362, 2021).
uveal melanoma (8 papers, 2012 to 2025). A melanoma derived from melanocytes of the uveal tract. "TGFβ has been shown to downregulate MHC-I on uveal melanoma cells in vitro, and TGFβ1 null mice exhibited an aberrant expression of MHC-I and MHC-II in tissues." (PMID 33149148, 2020).
vascular dementia (8 papers, 2020 to 2024). A degenerative vascular disorder affecting the brain. "Increased risk of sporadic vascular dementia has been associated with the Pro10Leu single-nucleotide polymorphism (SNP) in the TGFβ1 gene, which is known to impact the TGFβ1 protein level." (PMID 38132326, 2023).
Wilms tumor (8 papers, 2013 to 2022). An embryonal neoplasm characterized by the presence of epithelial, mesenchymal, and blastema components. "The aim of the present study was to investigate the rs1800468 (G-800A), rs1800469 (C-509T), rs1800470 (C29T), and rs1800471 (G74C) TGFB1 genetic polymorphisms and their haplotype structures in patients with Wilms Tumor (WT) and neoplasia-free controls." (PMID 34722128, 2021).
acute liver failure (7 papers, 2018 to 2025). Rapid deterioration of liver function causing encephalopathy and coagulopathy. "TSP1 is also reported to exacerbate azoxymethane-induced acute liver failure by activating TGFB1 signaling." (PMID 35357534, 2022). "In summary, the data presented here suggest that during acute liver failure, TGFβ1 expression is increased in the liver, contributing to increased circulating TGFβ1, which in turn regulates the neuroinflammation and neurological deficits associated with HE." (PMID 30940161, 2019). "During acute liver failure in patients due to acetaminophen toxicity, increased levels of hepatic TGFβ1 mRNA expression and circulating TGFβ1 levels have been observed when compared to healthy controls." (PMID 30940161, 2019). "We have previously demonstrated that hepatic TGFβ1 expression is upregulated in the AOM model of acute liver failure, which is consistent with other studies in response to a variety of hepatotoxins." (PMID 30940161, 2019). "TGFβ1 is released into the circulation after acute liver failure and binds TGFβR2 in neurons, resulting in increased CCL2 expression and decreased CX3CL1 expression leading to microglial activation." (PMID 30940161, 2019). "Increased circulating TGFβ1 following acute liver failure results in activation of neuronal TGFβR2 signaling, driving neuroinflammation and neurological decline during AOM-induced HE." (PMID 30940161, 2019). "Additionally, patients with APAP overdose have increased hepatic TGFβ mRNA and increased plasma TGFβ1 concentrations, indicating that TGFβ1 plays a role in the progression of acute liver failure." (PMID 41366830, 2025). "TGFβ1 was markedly elevated in both the liver tissue and the plasma in patients with acute liver failure, indicating that TGFβ1 may play a vital role in the regulation of ALI." (PMID 33707345, 2021). "Given that TGFβ1 can be packaged into exosomes, it is conceivable that the systemic TGFβ1 observed in our model of acute liver failure may be delivered via exosomes." (PMID 30940161, 2019). "Therefore, the aim of this study was to characterize hepatic and brain TGFβ1 signaling during acute liver failure and its contribution to HE progression using a combination of pharmacological and genetic approaches." (PMID 30940161, 2019). "In the current study, we have demonstrated that anti-TGFβ1 treatment had similar liver pathology after injection of AOM compared to IgG1 control mice, but had protective effects on the neurological complications associated with acute liver failure." (PMID 30940161, 2019). "Indeed, we have demonstrated that TGFβ1 itself is able to induce hyperpermeability of the blood–brain barrier during acute liver failure via the induction of matrix metalloproteinase-9 expression in brain endothelial cells and the alteration of tight junction protein expression." (PMID 30940161, 2019). "The data presented here suggest that increased circulating TGFβ1 following AOM-induced hepatic necrosis is influencing neurological function and neuroinflammation during acute liver failure." (PMID 30940161, 2019).
ankylosing spondylitis (7 papers, 2010 to 2025). An autoimmune chronic inflammatory disorder characterized by inflammation in the vertebral joints of the spine and sacroiliac joints. "Polymorphisms within the human Tgfb1 gene have a weak but significant association with Ankylosing Spondylitis and the T29C polymorphism in the Tgfb1 gene is associated with the genetic susceptibility to Spinal Osteophytosis." (PMID 20214815, 2010).
biliary tract cancer (7 papers, 2016 to 2024). "For example, expression and secretion of IL-6 and TGFβ1 are interconnected in biliary tract cancer cells, strengthening invasion, EMT and chemoresistance." (PMID 38672477, 2024). "In biliary tract cancer (BTC), EMT is induced by transforming growth factor-beta 1 (TGF-β1)." (PMID 26726879, 2016).
Fabry disease (7 papers, 2012 to 2025). Fabry disease (FD) is a progressive, inherited, multisystemic lysosomal storage disease characterized by specific neurological, cutaneous, renal, cardiovascular, cochleo-vestibular and cerebrovascular manifestations. "The rSNPs proposed here could modulate the clinical phenotype of Fabry disease, so we propose that IL10, TGFB1 and EDN1 genes be considered modifier/minor genes in FD, in charge of regulating its neuro-cardiovascular variant." (PMID 36138766, 2022). "In contrast to immortalized human podocytes exposed to lyso-Gb3, expression levels of COL4, FN1, HES1, and TGFβ1 were not elevated in urine-derived cells of Fabry disease patients." (PMID 30038331, 2018).
knee osteoarthritis (7 papers, 2017 to 2023). "Currently running preliminary trials in dogs with knee osteoarthritis have shown that the scaffold-TGFβ1 injected with dog adipose-derived mesenchymal stem cells at the site induced the formation of cartilage and improved the clinical picture of the animals (unpublished results)." (PMID 37509529, 2023).
mesenchymal tumors (7 papers, 2012 to 2025). "In the third category there were seven studies on epithelial mesenchymal transition (EMT)/TGFb/mesenchymal tumor (EMT/TGFb/Mes) according to the authors, with specific genes CDH1,2, VIM, and TGFb1,2,3 in studies as follows: E16 (CDH1,2, TGFb1, VIM), E24 (TGFb1), E31, E38, E39, E43 (CDH2), and E46." (PMID 40867621, 2025).
mucositis (7 papers, 2012 to 2022). Mucositis is inflammation and damage of the mucous membranes lining the mouth and other parts of the gastrointestinal (GI) tract. "In addition to mucositis, an increased radiation dose may lead to hyperactivation of transforming growth factor β1 (TGFβ1) bringing about excessive fibrosis, which may be responsible for impaired oral feeding and prolonged dependence on tube feeding." (PMID 36531036, 2022).
obstructive uropathy (7 papers, 2008 to 2023). "These cytokines constitute the major receptor-triggered apoptotic signals in nephrons following urinary obstruction, with a key role also played by transforming growth factor-beta 1 (TGF-β1), regarded as the pro-fibrotic factor “par excellence”." (PMID 28191787, 2017).
ocular hypertension (7 papers, 2013 to 2022). Abnormally high intraocular pressure. "The fact that αSMA expression was decreased in the TM of TGFβ1 transgenic mice and AdTGFβ1-treated rats, both of which have accompanying ocular hypertension, supports this notion." (PMID 23559862, 2013).
seminoma (7 papers, 2015 to 2026). A radiosensitive malignant germ cell tumor found in the testis (especially undescended), and extragonadal sites (anterior mediastinum and pineal gland). "Because these transcripts were identified as differentially expressed between area 1 and area 2 of the seminoma tumour ROIs, and TGFβ1 was identified as an upstream regulator by IPA, we next profiled TGFβ superfamily machinery within the seminoma area 1 and area 2 ROIs." (PMID 40693358, 2026). "In a study involving 577 tumor cases and > 700 controls, the TGFB1 Ex5-73C > T variant was positively associated with TGCT risk while Ex1-282G and 509C > T variants were linked with increased risks of seminoma and non-seminoma, respectively (Purdue at al., 2007)." (PMID 31842336, 2019).
Anorexia (6 papers, 2015 to 2023). Lack of desire to eat (loss of appetite). "Tumour-driven cytokines, such as growth differentiation factor 11, IL-1β, IL-6 leukaemiaia inhibitory factor, TNF-α, and TGFβ1 promote cancer cachexia with anorexia in the brain, proteolysis in the skeletal muscles, and browning in the WAT." (PMID 35406121, 2022).
autosomal dominant polycystic kidney disease (6 papers, 2019 to 2025). Autosomal dominant form of polycystic kidney disease. "Genetic variations in TGFβ1 are also associated with susceptibility to IgA nephropathy, autosomal dominant polycystic kidney disease (ADPKD), and CKD." (PMID 40807208, 2025).
endometritis (6 papers, 2022 to 2025). An acute or chronic, usually bacterial infectious process affecting the endometrium. "Therefore, elucidating the regulatory mechanisms of oxidative-stress-mediated TGFβ1/Smad3 signaling on ECM remodeling is crucial for understanding the pathogenesis of endometritis." (PMID 40646747, 2025). "This implies that in bovine endometritis, the TGFβ1/Smad3 signaling pathway may play a dual role in ECM remodeling." (PMID 40646747, 2025). "The results demonstrate that oxidative-stress-mediated endometritis significantly upregulates MMP2, MMP9, and the TGFβ1/Smad3 pathway activity, while suppressing COL-IV expression." (PMID 40646747, 2025). "This study found upregulated expressions of TGFβ1, Smad3, and MMP2/9 during bovine endometritis." (PMID 40646747, 2025).
follicular carcinoma (6 papers, 2015 to 2023). "DEX supplementation led to a slow downregulation of TGFB1 expression in static cell cultures or in follicular thyroid cancer cells grown for four hours on the RPM." (PMID 32033410, 2020).
follicular lymphoma (6 papers, 2010 to 2024). Follicular lymphoma is a form of non-Hodgkin lymphoma characterized by a proliferation of B cells whose nodular structure of follicular architecture is preserved. "Bulk RNA sequencing and histological assessment of high-tumor-burden follicular lymphoma tissues demonstrate a significant correlation between LTB, TGFB1, and CCL21 expression." (PMID 38038708, 2024).
hemorrhage (6 papers, 2014 to 2022). Loss of blood from the vascular compartment to the exterior or into nonvascular body space as a result of rupture or severance of the blood vessels. "Mice with conditional KO (cKO) of Tgfb1 from OPCs alone, displayed pronounced cerebral hemorrhage with degraded ZO-1." (PMID 34203192, 2021). "We used qPCR to compare blood TGFβ1 levels between the hemorrhage-prevalent peripheral group on the IgA PCA plot (SD1,6,7, and HD1-7) and the hemorrhage-absent group at the center (SD2-5 and ND5)." (PMID 29255469, 2017).
intracranial aneurysm (6 papers, 2015 to 2025). "The current study demonstrated that TGFB1 expression in PBMCs was significantly higher in the intracranial aneurysm group (comprising both UIA and RIA cases) compared to the control group." (PMID 40563991, 2025). "It wasfinally concluded that HIF1A-AS1 might participate in intracranial aneurysms byregulating VSMC proliferation through upregulating TGFβ1." (PMID 37801489, 2023).
invasive ductal carcinoma (6 papers, 2015 to 2025). "However, a growing number of studies have found that TAMEs can activate the TGFβ/Smads signalling axis in invasive ductal carcinoma cells through the production of TGFβ1." (PMID 40665579, 2025).
lipodystrophy (6 papers, 2015 to 2025). A congenital or acquired disorder characterized by abnormal loss or redistribution of the adipose tissue in the body. "Taken together, these experiments suggest that targeting FGF21 and TGFB1 may have utility for treatment of metabolic dysfunction associated with lipodystrophy and that murine housing temperature is an important variable to consider when studying therapeutic metabolic endpoints." (PMID 40663389, 2025).
metastatic prostate carcinoma (6 papers, 2016 to 2024). A carcinoma that arises from the prostate gland and has spread to other anatomic sites. "Clinicopathological characteristics of patients with metastatic prostate cancer according to TGFB1 polymorphisms." (PMID 34113577, 2021). "This study showed that genetic polymorphisms in TGFB1 were associated with unfavorable clinicopathological parameters including PSA value, Gleason score, and clinical T-stage patients with metastatic prostate cancer." (PMID 34113577, 2021). "We next analyzed the significance of TGFB1 genotype among patients with metastatic prostate cancer in the same manner." (PMID 34113577, 2021). "Patient backgrounds were comparable in the two subgroups of TGFB1 genotypes (rs2241716 and rs4803455) in patients with non-metastatic prostate cancer." (PMID 34113577, 2021).
rotator cuff tear (6 papers, 2016 to 2024). "Periodic intraperitoneal injections of LPA worsen the inflammatory milieu of rotator cuff tears (RCTs) in adult rats, increasing Tnfa and Tgfb1 at 6 weeks post tear and the number of inflammatory cells within the affected muscles." (PMID 36910157, 2023).
sialadenitis (6 papers, 2015 to 2025). Sialadenitis is an infection of the salivary glands. "In SS-associated sialadenitis, mast cells are situated next to fibroblasts and secrete TGFβ1, which stimulates collagen production in fibroblasts and promotes fibrosis." (PMID 40728992, 2025).
Splenomegaly (6 papers, 2009 to 2024). Abnormal increased size of the spleen. "The association of CMML-F with increased BM megakaryocytes and splenomegaly may be explained by megakaryocyte role in mediating bone marrow fibrosis possibly by releasing transforming growth factor beta 1 (TGF-β1)." (PMID 29262560, 2017).
Telangiectasia (6 papers, 2007 to 2025). Telangiectasias refer to small dilated blood vessels located near the surface of the skin or mucous membranes, measuring between 0.5 and 1 millimeter in diameter. "A boost and the XRCC1 (R399Q) polymorphism each contribute to the risk of telangiectasia, whereas an acute reaction and the TGFβ1(C-509T) polymorphism make independent contributions to the overall risk of fibrosis." (PMID 17325707, 2007).
tendinitis (6 papers, 2013 to 2023). Inflammation of a tendon, usually resulting from an overuse injury. "In tendinitis repair, shockwaves increase transforming growth factor beta 1 (TGFβ1) and insulin-like growth factor 1 (IGF-1)." (PMID 31936603, 2020).
tubulointerstitial nephritis (6 papers, 2014 to 2019). "Additionally, previous studies demonstrated that gentamicin increased macrophage infiltration and elevated TGFβ1 level leading to the progression of tubulointerstitial nephritis." (PMID 27727327, 2016).
uremia (6 papers, 2016 to 2025). A clinical syndrome associated with the retention of renal waste products or uremic toxins in the blood. "However, under conditions mimicking uremia, i.e., in the presence of indolic toxins, a concentration of TGFβ1 comparable to levels found in hemodialysis patients amplified the upregulation of IL-8 and MCP-1 induced by indolic toxins." (PMID 41003499, 2025).
autoimmune encephalitis (5 papers, 2017 to 2025). Inflammation of the brain secondary to an immune response triggered by the body itself. "Finally, one may keep in mind that, although TGFB1 is generally considered as an overall anti-inflammatory cytokine, robust in vivo data previously showed that overexpression of TGFB1 in the CNS aggravates experimental autoimmune encephalitis." (PMID 28981455, 2017).
Avellino corneal dystrophy (5 papers, 2008 to 2024). "TGFβ1-induced expression of transforming growth factor β-induced protein (TGFBIp) and extracellular matrix (ECM) genes plays a major role in the development of granular corneal dystrophy type 2 (GCD2: also called Avellino corneal dystrophy)." (PMID 26553048, 2015).
carcinoma in situ (5 papers, 2013 to 2019). "Interestingly, the key pathway emphasized in AK versus uninvolved skin was TGFβ1, consistent with the nature of AK being carcinoma in situ." (PMID 27612149, 2016).
demyelination (5 papers, 2013 to 2023). "It is believed that the main role of TGFβ1 is to maintain immune tolerance and that it protects against inflammatory demyelination." (PMID 24069377, 2013).
epithelial ovarian tumors (5 papers, 2012 to 2019). "Ovarian epithelial tumor cells showed concurrent up-regulation of miR-200, down-regulation of the four target genes (ZEB1, ZEB2, TGFβ1 and TGFβ2), and up-regulation of effector genes that were negatively regulated by the target genes." (PMID 28623900, 2017).
Gliosis (5 papers, 2018 to 2024). Gliosis is the focal proliferation of glial cells in the central nervous system. "Indeed, as supported by the molecular histology of SC periplaques, TGFB1 may fuel a process of extensive astrocytosis that possibly stems from pre-existing sites of plaque-associated gliosis." (PMID 31779094, 2019). "Upregulation of Tenascin C has also been linked to growth factors and cytokines such as TGFβ1, interleukin 1 and TNFα, which have been associated with retinal degenerative disorders, suggesting that Tenascin C may contribute to gliosis." (PMID 30176221, 2018).
Graves disease (5 papers, 2021 to 2025). Graves' disease is an autoimmune disorder that leads to overactivity of the thyroid gland (hyperthyroidism).It is caused by an abnormal immune system response that causes the thyroid gland to produce too much thyroid hormones. "The authors observed an elevated mRNA expression of TGFB1 in PTC (n=06) compared to multinodular goiter (n=22, p=0.015) and Graves’ disease (n=08, p=0.001)." (PMID 33905626, 2021).